IDO1 (indoleamine 2,3-dioxygenase 1)
Diseases named in the same sentence as IDO1 in open-access papers (continued):
Sharing a sentence is not in itself a finding about the gene and the disease.
tumor (continued). "In mice lacking Dock2, IFNγ production is increased in multiple T cell populations, including CD8+ and γδ T cells, and administrating IFNγ to tumour organoids induces robust IDO1 expression suggesting this response is driven by immune cell IFNγ production." (PMID 39242821, 2024). "Results showed that 50 of 93 (54.1%) TNBC tissues have positive IDO-1 expression in cytoplasm of parenchymal cells of the tumor." (PMID 37981615, 2024). "Constitutive expression of TDO in tumor cells can be regulated similarly to that of IDO1, involving signaling via the COX-2/PGE2 and AhR pathways, while other TDO-regulating pathways have been described as well." (PMID 39211039, 2024). "These preliminary observations confirm the moonlighting ability of IDO1 to switch from the catalytic to the signaling function, allowing tumor cells to resist the enzymatic inhibition of IDO1 by epacadostat." (PMID 38333210, 2024). "IDO1 staining in tumor cells was detected in 90 of 96 carcinomas (94%), whereas in six carcinomas, tumor cells were immunonegative." (PMID 39061522, 2024). "Tumors elevate levels of crucial catabolic enzymes like ARG1 or IDO1, leading to decreased arginine and tryptophan levels in the tumor." (PMID 39420203, 2024). "IDO1 is essential for recruiting MDSCs to lymph nodes, spleen, and tumor tissues for regional immunosuppression." (PMID 39371092, 2024). "Next, we examined genetic alterations in the IDO1 gene in HNSCC tumors using cBioPortal, which revealed that IDO1 was altered in 33 out of 504 HNSCC tumor samples (6.5% of the samples)." (PMID 38736462, 2024). "Further, the CBM588-induced immunogenic conversion of the tumor-infiltrating lymph nodes is related to the Indoleamine 2,3-Dioxygenase 1/Inerleukine 10 (IDO1/IL-10) axis upon PD-1 blockade (IDO1 catalyzes the initial step in the degradation of tryptophan)." (PMID 39338971, 2024). "According to the previous study, IDO1 expression has been shown to be positive for tumor B-cell infiltration." (PMID 38539263, 2024). "Indoleamine 2,3-dioxygenase 1 (IDO1), an enzyme that catalyzes the breakdown of tryptophan to kynurenine, is constitutively expressed by a wide variety of human tumor cell types as well as by dendritic cells that localize to tumor-draining lymph nodes." (PMID 39054462, 2024). "Numerous tumor types upregulate IDO1 to expedite tryptophan breakdown and establish an immunosuppressive milieu." (PMID 39312339, 2024). "The direction of these changes was determined by analyzing the mRNA synthesis of specific factors (cytokines, Arg1, NOS2, Ido1) in TAS cells of tumor-bearing and other groups of the experimental mice." (PMID 38455363, 2024). "Inhibition of relevant immunosuppressive pathways identified in the tumor microenvironment (e.g., PD-1, indoleamine-2,3-dioxygenase 1 (IDO1)) can be an effective strategy to strengthen antitumor immunity and stop tumor growth." (PMID 39272837, 2024). "Markedly upregulated IDO1 was seen on both immune and tumor cells in hot/warm vs. cold immune state groups." (PMID 38714665, 2024). "There was also significant enrichment (P < 0.05) of cellular interaction between PD-1+ Memory Cytotoxic T cells and Tumor cells, Monocytes, and IDO1+ cells, among others." (PMID 39333065, 2024). "The induction of the KP regulating enzyme IDO-1, KP activation, and TRP depletion are all implicated in the establishment of pregnancy-related immunological tolerance and tumor tenacity." (PMID 38255925, 2024). "Specifically, the activation of AhR triggers the up-regulation of IL-6, which subsequently mediates signal transducer and activator of transcription 3 (STAT-3) signaling, promoting the expression of IDO-1 in tumor cells." (PMID 39062529, 2024).
tumor (continued). "Tumors with diffuse immune infiltration and increased tumor-immune spatial interactions had higher presence of IDO1, PD-L1, PD-1 and Tim-3, while focal immune niches had more CD163 macrophages and a preliminary worse outcome." (PMID 39026018, 2024). "IDO1 inhibitors prevent the tryptophan deprivation and accumulation of kynurenine (and also its metabolites) in the cells and in the tumor microenvironment." (PMID 38396769, 2024). "In parallel, β-catenin promotes Tregs differentiation by stimulating tumor production of IDO1 and synergistically suppressing the immune response." (PMID 38685033, 2024). "For more effective immunotherapy, developing a new nanomedicine capable of efficiently co-delivering STING agonists and IDO1 inhibitors to tumor tissues is essential." (PMID 38966855, 2024). "A tumor-friendly immunological microenvironment can be created by IDO1 and Kyn metabolites, and aryl hydrocarbon receptors can be activated as part of this process." (PMID 38539263, 2024). "Statistically significant correlations existed between a higher percentage of IDO1-positive tumor cells, lower mitotic counts, and increased estrogen receptor expression." (PMID 39061522, 2024). "IDO1 expression in more than 10% of tumor cells was determined as the threshold for reaching significance levels for ER-α status and mitotic count between IDO1-positive and IDO1-negative tumors." (PMID 39061522, 2024). "The high expression of IDO1 in HPV+ tumors can be explained in the context of high inflammation usually seen in this type of tumor in comparison with HPV− cases." (PMID 38736462, 2024). "We used the ESTIMATE method to explore the correlation between TME and the IDO1 gene in different tumor tissues." (PMID 38539263, 2024). "IDO1 is significantly positively correlated to genes with immune-related functions, further strengthening the role and relation of IDO1 to tumor immunity." (PMID 38736462, 2024). "IDO1 is an intracellular heme-containing enzyme of the kynurenine pathway with antimicrobial, immunosuppressive, and tumor-promoting functions." (PMID 39061522, 2024). "Here, we employed lipid nanoparticles (LNPs) to deliver either non-specific pDNA and siRNA, or constructs targeting two prominent immunotherapeutic targets OX40L and indoleamine 2,3-dioxygenase-1 (IDO), to tumours in vivo." (PMID 38493950, 2024). "The tryptophan-degrading enzyme indoleamine 2,3-dioxygenase 1 (IDO1) is a plastic immune checkpoint molecule that potently orchestrates immune responses within the tumor microenvironment (TME)." (PMID 38333210, 2024). "In comparison, tumor cells with apical IDO1 staining were restricted to tumor areas with tubular, papillary, or cystic growth; the staining was always granular." (PMID 39061522, 2024). "Since the other altered-excluded carcinoma contained 2% IDO1-positive tumor cells, the existence of additional immunosuppressive mechanisms within the tumor area appears likely." (PMID 39061522, 2024). "Immunosuppressive tumor microenvironment is one of the important reasons leading to the failure of tumor therapy, and IDO1 which regulates the metabolism between Trp and F-Kyn, is demonstrated to be an archcriminal for immune escape." (PMID 38725031, 2024). "Taken together, ample evidence supports the role of IDO1 as an immunosuppressive molecule in the tumor microenvironment." (PMID 39239507, 2024). "Indoleamine 2,3-dioxygenase 1 (IDO-1) is thought to inhibit the proliferation of microbes, tumor cells, and activated T lymphocytes, possibly by catabolizing the necessary amino acid tryptophan." (PMID 38719907, 2024). "In particular, IDO1 is overexpressed and constitutes a poor prognostic marker in many tumours including endometrial cancer, laryngeal squamous cell carcinoma, melanomas, gastric cancer, hepatocarcinoma, and cervical cancer." (PMID 39351094, 2024).
tumor (continued). "In preclinical mouse models, IDO1 inhibition has been demonstrated to synergize with PD-L1 inhibition in delaying tumor growth and prolonging survival." (PMID 39054485, 2024). "In tumor cells, LINC02096 inhibits the ubiquitination of histone methyltransferase MLL1, which enhances the levels of H3K4me3 in the promoter regions of PD-L1 and IDO-1, thereby undermining anti-tumor immunity." (PMID 39403382, 2024). "Epacadostat selectively blocks the expression of IDO1, but the TDO pathway can play a potential compensatory role in causing tumor immunosuppression." (PMID 39728172, 2024). "On the other hand, tumor cell-specific knockdown of IDO1 can inhibit tumor growth, decrease regulatory T-cell accumulation and improve survival in murine cancer models." (PMID 39211039, 2024). "These seemingly contradictory observations prompted us to study the functional interactions between IDO1, epacadostat, tumor cells, and T cells in more mechanistic detail." (PMID 36812891, 2023). "Next, we evaluated clinical responses and quantitative changes of IDO1 in OSCC patients following tumour surgery." (PMID 35963900, 2023). "For instance, the IDO1 inhibitor, LY3381916, combined with the PD-L1 inhibitor, can minimize the activity of IDO1, eventually increasing the number of T cells and promoting anti-tumor immunity." (PMID 38264667, 2023). "Epacadostat is a selective indoleamine 2,3-dioxygenase-1 (IDO1) enzyme inhibitor, currently under investigation in several tumor types." (PMID 37626654, 2023). "Among the top 10 upregulated genes, expression of IDO1, a critical factor in tumor progression, was the most significantly enhanced." (PMID 36831659, 2023). "Significantly, tumor samples from patients who underwent surgical resection after CAR T cell infusion revealed upregulation of IDO1 and increased T regulatory cells, implying the possibility of GBM escape mechanisms reinstating an immunosuppressive milieu." (PMID 36900311, 2023). "Discussion: Our results indicate that IDO1 has the potential to promote the progression of OS that is related to miRNAs mediated tumor immunity." (PMID 37284323, 2023). "Results from in vitro, in vivo and clinical studies have revealed that the inhibition of IDO1 led to tumour suppression." (PMID 37041200, 2023). "According to the Tumor Immune Dysfunction and Exclusion (TIDE) tool, the results exhibited that the Exclusion score, CAF score, PD-1, CTLA4, IDO1, and TIGIT score of the high-risk group were higher than those of the low-risk group." (PMID 37880682, 2023). "IDO1 is undoubtedly a stimulator of CRC progression, and IDO1 downstream metabolites regulate tumor cell growth." (PMID 36755301, 2023). "Given the evidence that IDO1 promotes T-cell anergy and suppresses tumour control, studies were carried out to examine the potential of inhibiting IDO1 to reduce tumour growth to unravel its role in BrCa progression." (PMID 37041200, 2023). "We also report early in vivo data in support of the potential therapeutic efficacy of the dual IDO1/TDO2 inhibitor AT-0174 as a part of immuno-therapeutic treatment that disrupts tumor metabolism and enhances anti-tumor immunity." (PMID 37226257, 2023). "The increased expression of Stat1, Ido1, and H2ab1 suggested that the IFNγ signal in the tumor was upregulated and accompanied by elevated IFNγ expression in CTLs." (PMID 36793737, 2023). "In preclinical studies, inhibition of both IDO1 and an immune checkpoint pathway provided greater control of tumor growth than immune checkpoint inhibition alone." (PMID 37087488, 2023). "Navoximod and indoximod are other IDO1 inhibitors with tumor growth suppressive activity but generally lack information about MDSC‐related changes." (PMID 37547175, 2023). "The genetic silencing of IDO1 has consistently been reported to reduce the abundance of Treg cells and potentiate cytotoxic T cells, and enhance the anti-tumor immunity in metastatic hepatocellular carcinoma." (PMID 37631380, 2023).
tumor (continued). "IDO1 reduces tryptophan (Trp) levels in the tumor microenvironment (TME) that are necessary for T cell proliferation and function." (PMID 36445328, 2023). "At the tumor site, based on CD8+ and interferon γ, IDO-1 is usually overexpressed in the tumor environment." (PMID 37513483, 2023). "At tumor sites, MDSCs release IL-10 and free radicals such as peroxynitrite, and they also express indolamine 2,3 dioxygenase (IDO1) and arginase-1 (ARG1)." (PMID 37189689, 2023). "Regarding the potential role of IDO1 activity affecting MDSCs, we found that CR tumors with greater IDO1 activity, possessed higher tumor-infiltrating MDSC populations when compared to CS tumors." (PMID 37226257, 2023). "This is intriguing, because IDO1 catalyzes the conversion of Trp to Kyn, which can suppress T-cell activity and allow tumor cells to escape clearance by the immune system, particularly through Kyn-mediated aryl hydrocarbon receptor (AHR) activation." (PMID 37985999, 2023). "Inhibition of IDO1 function has been shown to elevate tumour-infiltrating CD8 T cells in the mouse, and in vitro." (PMID 37766359, 2023). "In ICB immunotherapy for ccRCC, the C4ORF19 expression level correlated significantly with clinicopathological stage, tumor grade, and key genes (i.e., IDO1)." (PMID 38288096, 2023). "IDO1 is an immune response regulator involved in the suppression of the anti-tumor immune response and immune evasion." (PMID 38149244, 2023). "Accordingly, it is less a unique aspect of IDO1 function that dictates its ability to foster tumor-promoting inflammation so much as a unique set of regulatory controls that has been superimposed because IDO1’s activity is not otherwise needed." (PMID 37182174, 2023). "IDO1 is considered to be a new target for tumor therapy, and inhibition of IDO1 activity by using IDO1 inhibitors can increase patient survival." (PMID 37817770, 2023). "This suggests also that the sensitivity of malignant cells to treatment with IDO1 inhibitors varies between tumor types and points to the complex role of the kynurenine pathway in cancerogenesis." (PMID 38201550, 2023). "By targeting both ERO1a and IDO1, we harnessed their unique modulation potential offered on the myeloid cell compartment and the tumor secretome." (PMID 38187398, 2023). "In ovarian cancer cells, IDO1 expression increased the number of CD8+ tumor-infiltrating T cells expressing PD-1, with a similar induction by kynurenine." (PMID 37296860, 2023). "A series of tumour biopsies was collected from the dose escalation and expansion cohorts pre- and on-treatment, and IHC of IDO1 was performed." (PMID 37041200, 2023). "In mouse tumor models, blocking IDO1 activity with small-molecule inhibitors has been successful in delaying metastasis development, impairing tumor outgrowth, and prolonging survival." (PMID 37630387, 2023). "Blocking IDO1-induced anti-cancer Th1 cytokines within the tumor microenvironment facilitates the overall eradication of cancer cells, even around the surrounding stroma." (PMID 36765706, 2023). "A recent study also showed that tumor cells that produce IDO1 are constitutively dependent on COX2 and PGE2 via the PKC and PI3K pathways and continuously prevent T-cell infiltration." (PMID 36983678, 2023). "IFN-γ regulates immune escape correlated with the overexpression of immune checkpoint receptors including PD-L1 and IDO1, which eliminates T cell activity in tumor tissues." (PMID 37334368, 2023). "IDO1 contributes to tumor immune tolerance by inhibiting T-cell proliferation, inducing T-cell apoptosis, promoting the differentiation of naïve T cells into regulatory T cells, and regulating the pool of peptides available for antigen presentation." (PMID 37087488, 2023). "A preclinical study has shown that COX-2 inhibition can reduce IDO1 levels and inhibit tumor growth and metastasis." (PMID 37924140, 2023).
tumor (continued). "For IDO1, a further assessment of expression on tumour epithelium was the most optimal method using a (0 = 0%, 1 = 1–20%, 2 ≥ 20%) scoring system." (PMID 37527282, 2023). "The results of clinical trials performed to evaluate promising IDO1 inhibitors have been disappointing, which highlights the need for a deeper understanding of the precise effector mechanisms of tumor metabolism in vivo." (PMID 36755301, 2023). "Collectively, we found that Abrine has an anti-tumor immune escape and promote immune response effect by inhibiting IDO1." (PMID 37334368, 2023). "IDO‐1 can activate Tregs and consume tumor‐infiltrating CTLs by metabolizing Trp into Kyn, while PD‐L1, which is overexpressed on tumor cells, can trigger CTL depletion through interaction with PD‐1 expressed on T cells." (PMID 36599655, 2023). "At one level, IDO1 expression promotes immune tolerance to tumor antigens, thereby helping tumors evade adaptive immune control." (PMID 37182174, 2023). "The overexpression of IDO1 in tumor cells and multiple immune cells in the tumor microenvironment induces T‐cell anergy and thus promotes immune tolerance." (PMID 38037752, 2023). "IDO1 functions in suppression of anti-tumor immunity by degrading tryptophan and producing a series of toxic kynurenine metabolites to promote immune evasion of tumors, but the inhibitor of IDO1 failed in a phase 3 clinical trial." (PMID 37228646, 2023). "IDO1 inhibitors such as 1-methyl-D, L-tryptophan (1-MT, NLG8189) and navoximod (NLG919), can effectively inhibit IDO enzymes and relieve tumor immunosuppression." (PMID 36927803, 2023). "1-MT was taken off from the polymeric carrier in the presence of esterase and efficiently intervened IDO1 mediated immunosuppressive tumor microenvironment." (PMID 36927803, 2023). "CD8+ T cells in the tumor microenvironment are capable of producing interferon-γ (IFNγ), which stimulates the upregulation of PD-1/PD-L1 and IDO1 gene expression." (PMID 37153654, 2023). "Epacadostat (firstly named INCB024360) was one of the most promising catalytic inhibitors targeting IDO1 to foster anti-tumor immune responses." (PMID 37122718, 2023). "Indoleamine 2,3-dioxygenase 1 (IDO1) is recognized as an immune checkpoint molecule that is expressed in 50% of human tumors and plays a major role in tumor escape mechanisms." (PMID 37122718, 2023). "It has been demonstrated in in vivo and in vivo studies that combination treatment of indoleamine 2,3 dioxygenase 1 inhibition and chemotherapy drug(s) limits tumor growth." (PMID 37367861, 2023). "Although there has been a strong emphasis on understanding the role of IDO1 or IDO2 in tumor viability, there is increasing attention to downstream enzymes such as KMO." (PMID 37296860, 2023). "By restoring tryptophan, indoleamine 2,3-dioxygenase 1 (IDO1) inhibitors aim to reactivate anti-tumor T cells." (PMID 36812891, 2023). "Conversely, in the context of an IDO1-inducing, inflammatory environment, it is likely that the tumor will become specifically reliant on IDO1 in a manner analogous to the concept of ‘oncogene addiction’." (PMID 37182174, 2023). "In tumor lysates from mice received cisplatin treatment or RT, we found that Kyn and IDO1 levels were increased." (PMID 37670034, 2023). "The IDO1 inhibitor epacadostat is currently undergoing clinical investigation in various tumor types, including CRC." (PMID 36755301, 2023). "High IDO1 expression in tumour-infiltrating immune cells was significantly correlated with advanced stages [Spearman’s rank correlation (SRC), p = 0.027] and reduced progression-free survival (multivariate Cox regression, p = 0.034)." (PMID 35963900, 2023). "High correlation was observed between PD-L1 and IDO1 expressions (Pearson correlation co-efficient = 1) and subsequently high IDO1 expression in tumour cells was found to be significant for PFS (p = 0.006) and OS (p = 0.034)." (PMID 37527282, 2023).